LEP (leptin)
Diseases named in the same sentence as LEP in open-access papers (continued):
Sharing a sentence is not in itself a finding about the gene and the disease.
lung adenocarcinoma (7 papers, 2014 to 2025). A carcinoma that arises from the lung and is characterized by the presence of malignant glandular epithelial cells. "In conclusion, the results of the present study indicate a strong association between serum leptin level and its prognostic value in patients with advanced lung adenocarcinoma during cisplatin/pemetrexed chemotherapy." (PMID 24932291, 2014). "Serum from consenting patients with lung adenocarcinoma were obtained for the measurement of leptin and associated tumor biomarkers." (PMID 24932291, 2014). "Patients with adenocarcinoma of the lung were found to have higher serum leptin levels compared to patients with squamous cell carcinoma and other types of NSCLC." (PMID 41463203, 2025). "Leptin can also block the endoplasmic reticulum stress-related pathway, preventing apoptosis and promoting proliferation in lung adenocarcinoma A549 cells." (PMID 38571500, 2024). "These were able to abolish and reverse the proliferative and the anti-death roles promoted by the survival adipocytokine, leptin, also in the presence of lung adenocarcinoma pleural fluids promoting cancer growth in the milieu." (PMID 35740047, 2022). "In a study of brain metastasis of lung adenocarcinoma, activation of leptin signaling was highlighted in the context of the lnc-REG3G-3-1high/miR-215-3plow axis." (PMID 33799880, 2021). "In the present study, the serum leptin level was demonstrated in patients with lung adenocarcinoma to show a trend that corresponded to the cisplatin/pemetrexed chemotherapy response." (PMID 24932291, 2014). "This is the first study, to the best of our knowledge, that demonstrates that serum leptin has prognostic indications in patients with lung adenocarcinoma who are treated with cisplatin/pemetrexed chemotherapy in the first-line setting." (PMID 24932291, 2014). "We hypothesized that leptin expression may be a determinant for prognosis in lung adenocarcinoma patients with cisplatin/pemetrexed chemotherapy." (PMID 24932291, 2014). "The results indicated that the serum leptin level has prognostic indications in patients with advanced lung adenocarcinoma during cisplatin/pemetrexed chemotherapy, which indicates that it may be a useful marker for the prognosis of cancer patients undergoing chemotherapy treatment." (PMID 24932291, 2014). "Similar observations showed that leptin overexpression decreased the cisplatin-mediated ER stress unfolded protein response pathways PERK and ATF6 to promote lung adenocarcinoma A549 cell proliferation." (PMID 33799880, 2021).
lymphopenia (7 papers, 2006 to 2025). Reduction in the number of lymphocytes. "Lack of leptin in mice (ob/ob) or acute starvation develop thymus atrophy, T cell lymphopenia and spleen reduction, which are reversible with exogenous leptin administration, proving that leptin signalling is necessary for correct immune organ function." (PMID 33673730, 2021). "Leptin administration reversed the starvation-induced lymphopenia of bone marrow B cells, indicating an important role of central leptin in the immune system." (PMID 29910742, 2018). "Since leptin is required for lymphopoiesis, leptin receptor-deficient mice have fewer circulating B- and CD4+ T-lymphocytes and are unable to correct irradiation-induced lymphopenia." (PMID 22313574, 2012). "The study looking at the neuroendocrine stress response found that, in keeping with previous studies, lymphopenia is not related to increased cortisol levels and provided new data on a possible relationship of the low lymphocyte counts with increased prolactin and low leptin levels." (PMID 16859512, 2006).
postpartum depression (7 papers, 2018 to 2024). A type of clinical depression that occurs after childbirth. "The project will provide insights into the association between adiponectin and leptin with postpartum depression and infant neurodevelopment, ultimately promoting improved care and quality of life for these groups." (PMID 39453947, 2024). "In addition, in relation to hormones, a sub-variant of postpartum depression, leptin levels tended to decrease in the continuous exercise group of this study." (PMID 38684812, 2024). "Second, the interactive contactless exercise lowered metabolic control and stress response factors (TG, Insulin, Leptin, and Cortisol) that contribute to postpartum depression." (PMID 38684812, 2024). "Although there was no significant change in serotonin levels in this study, positive changes in leptin and cortisol levels indicated that continuous contactless exercise via an online platform can regulate the metabolic mechanism of postpartum depression." (PMID 38684812, 2024). "And in women, elevated early postpartum leptin levels, which possibly coincide with retained leptin resistance, was shown to be predictive of postpartum depression." (PMID 35222059, 2021). "Yildiz and colleagues reported that serum levels of adiponectin and leptin were high in women with postpartum depression." (PMID 33667284, 2021). "Esketamine combined with ropivacaine hydrochloride used in labor analgesia can significantly reduce the incidence of postpartum depression after delivering without increasing related side effects, which may be related to the regulation of leptin, norepinephrine, and epinephrine in the serum." (PMID 38166663, 2024).
Prader-Willi syndrome (7 papers, 2009 to 2024). "This cannot be relevant to Prader-Willy syndrome cases or genes related to leptin and melanocortin signalling, which have a higher influence on BMI." (PMID 38474710, 2024). "The results obtained in our study also do not exclude the presence of functional relationships between nesfatin-1 and leptin in Prader-Willi syndrome." (PMID 36904239, 2023). "Previous evaluation included methylation test for Prader-Willi syndrome, thyroid function test, leptin level, melanocortin 4 receptor gene sequencing, cortisol level, bone age, and HbA1c were all normal." (PMID 25927380, 2015). "In Prader-Willi Syndrome, loss of MAGEL2 may likewise abolish leptin responses in POMC hypothalamic neurons." (PMID 23341784, 2013).
respiratory failure (7 papers, 2018 to 2023). The significant impairment of gas exchange within the lungs resulting in hypoxia, hypercarbia, or both, to the extent that organ tissue perfusion is severely compromised. "The adiponectin/leptin ratio was associated with respiratory failure in unadjusted analysis (OR 0.75, CI 0.61–0.91) and after adjustment for age, sex, and BMI (OR 0.69, CI 0.52–0.91)." (PMID 36960389, 2023). "Resveratrol was also observed to reduce the secretion of leptin, an adipokine that has been implicated to be a contributing factor in the development of respiratory failure and ARDS in SARS-CoV-2 infected patients." (PMID 34372541, 2021). "According to this paper, excessive adipose tissue and leptin production may drive the development of respiratory failure and ARDS in SARS-CoV-2 infected patients." (PMID 34728695, 2021). "If leptin indeed plays a crucial role, medication that reduces leptin production might attenuate pulmonary edema, respiratory failure and the need to be admitted to the intensive care." (PMID 32844126, 2020). "In order to investigate the levels of leptin in SARS-CoV-2 critically ill patients, we performed a cross-sectional study measuring serum leptin levels in infected patients with respiratory failure." (PMID 32844126, 2020). "Models of animals lacking the gene responsible for leptin production exhibit marked abnormalities in breathing control, leading to respiratory failure (hypoxemia and hypercapnia)." (PMID 29975721, 2018).
ulcerative colitis (7 papers, 2011 to 2022). An inflammatory bowel disease involving the mucosal surface of the large intestine and rectum. "Moreover, studies have suggested that adipokines secreted by adipose tissue (TNFα, IL-1, IL-6, leptin, resistin and adiponectin) are closely associated with inflammatory bowel diseases such as ulcerative colitis." (PMID 22073943, 2011). "Serum leptin levels in patients with ulcerative colitis are higher compared with those in healthy controls." (PMID 28170448, 2017).
acne (6 papers, 2012 to 2024). An inflammatory process of the sebaceous glands which is characterized by comedones, nodules, papules and/or pustules on the skin. "Ductal hypoxia, occurring in the obstructed follicles, has been also linked to the development of acne and hypoxia-inducible factor 1-α (HIF-1α) was shown to promote leptin expression." (PMID 33260746, 2020). "Interestingly, isotretinoin (the most effective anti-acne agent) altered adiponectin levels and decreased leptin levels, which were significantly lower in the acne patients compared with the control group already at the basal levels." (PMID 33260746, 2020). "There is a limited number of studies evaluating leptin in acne vulgaris." (PMID 33008429, 2020). "The potential role of leptin in acne vulgaris is still under discussion." (PMID 33008429, 2020). "While through augmenting Th17/IL-17 signaling and enhancing the secretion of pro-inflammatory cytokines by immune cells, leptin may also be involved in generating the pathological immune-milieu characteristic for lesional acne skin." (PMID 33260746, 2020). "Interestingly, the findings that leptin and other factors from the “Western diet” may activate the mTORC1 pathway, which, in turn, further enhances leptin production, suggest a possible role for the leptin-mTORC1 axis to link nutrition with the development of acne." (PMID 33260746, 2020). "Acting in an autocrine manner, leptin may be involved in an increased lipid metabolism and pro-inflammatory cytokine/enzyme production by activating the STAT3 pathway as observed in human SZ95 sebocytes in vitro, which resembled the changes detected in the sebum of acne patients." (PMID 33260746, 2020).
acquired generalized lipodystrophy (6 papers, 2018 to 2025). Acquired generalized lipodystrophy belongs to a group of lipodystrophic syndromes characterized by loss of adipose tissue, and is a syndrome of insulin resistance that leads to increased cardiovascular risk. "Currently, metreleptin (Myalept), a recombinant human leptin analog, is used as an injectible to treat complications of leptin deficiency in patients with congenital or acquired generalized lipodystrophy." (PMID 32164196, 2020). "Metreleptin for injection, an analog of leptin, is the first FDA-approved therapy as an adjunct to diet to treat the complications of leptin deficiency in patients with congenital generalized or acquired generalized lipodystrophy in the USA." (PMID 40415699, 2025). "Leptin replacement may also be a viable treatment for congenital generalized or acquired generalized lipodystrophy." (PMID 31067764, 2019).
acromegaly (6 papers, 2017 to 2024). Acromegaly is an acquired disorder related to excessive production of growth hormone (GH) and characterized by progressive somatic disfigurement (mainly involving the face and extremities) and systemic manifestations. "Ghrelin and leptin levels decrease, while adiponectin levels increase in patients with acromegaly, reflecting a decrease in healthy adipose tissue." (PMID 35355553, 2022). "In general, serum leptin levels in patients with acromegaly are reduced, while other adipocytokines have been assessed in a few studies with inconsistent conclusions." (PMID 33414826, 2020). "For example, individuals with acromegaly and bGH mice have decreased levels of leptin and adiponectin, while treatment increases at least leptin levels." (PMID 28933734, 2017). "GH reduces leptin gene expression in VAT, and in acromegaly, circulating leptin levels are low and rise with surgical or pegvisomant therapy." (PMID 36176462, 2022). "Some studies have indicated elevated leptin levels and decreased response to growth hormone replacement therapy (GHRT), as well as lower adiponectin levels compared with patients with acromegaly but similar to those of healthy individuals." (PMID 39610397, 2024). "However, changes in leptin and IR with acromegaly treatment do not consistently correlate, and whether low leptin contributes to IR in acromegaly and its rise to IR improvement is unknown." (PMID 36176462, 2022).
acute pancreatitis (6 papers, 2017 to 2024). An acute inflammatory process that leads to necrosis of the pancreatic parenchyma. "Leptin is also associated with persistent hyperglycemia, as shown in the early course of acute pancreatitis." (PMID 33935782, 2021). "Acute pancreatitis is associated with high levels of leptin in serum and pancreas, suggesting the role for such a hormone as a marker for adipose tissue necrosis." (PMID 31091785, 2019). "In the clinical setting, higher plasma leptin concentrations are associated with acute pancreatitis; thus, leptin may be a possible predictor of disease severity." (PMID 33935782, 2021). "One study showed a significant inverse association between leptin and intra-pancreatic fat deposition (determined with the use of magnetic resonance imaging), independent of abdominal fat distribution in individuals after an attack of acute pancreatitis." (PMID 34684558, 2021). "Individuals with NODAP have abnormal iron metabolism and it is conceivable that the association between hepcidin and leptin observed in the present study could play a part in the complex pathophysiology of glucose derangements after acute pancreatitis." (PMID 34684558, 2021). "In agreement with this hypothesis, beneficial effects of leptin on acute pancreatitis have been evidenced in ischemia/reperfusion." (PMID 31091785, 2019). "It has been suggested that leptin has anti-inflammatory effects and that the administration of high doses of leptin could result in neutrophil inhibition in the lungs of rats with acute lung injury induced by acute pancreatitis." (PMID 30116155, 2018). "When acute pancreatitis is induced, ob/ob mice exhibit higher pathologic scores and intestinal permeability relative to wild-type mice, indicating that absence of leptin signaling aggravates intestinal inflammation." (PMID 33935782, 2021). "However, no clinical trials have examined exogenous leptin treatment in patients with acute pancreatitis." (PMID 33935782, 2021). "The difference in leptin and adiponectin levels between SAP and mild acute pancreatitis (MAP) patients were not significant (SMD = 0.30, 95% CI: -0.08 to 0.68, z = 1.53, P = 0.127 and SMD = 0.11, 95% CI: -0.17 to 0.40, z = 0.80, P = 0.425, respectively)." (PMID 38218787, 2024).
allergic asthma (6 papers, 2013 to 2022). A asthma with a basis in a pathological type I hypersensitivity reaction. "In summary, our results suggest leptin as a key risk factor in the development of allergic asthma in obese subjects through induction of the UPR factor XBP1s that promotes survival of pro-allergic lymphocytes and their cytokine expression." (PMID 29891850, 2018). "Further studies are warranted to understand the complex yet critically important relationship between serum/plasma leptin levels, leptin receptor expression, and severity of allergic asthma." (PMID 23383125, 2013). "Furthermore, leptin-deficient Ob−/− asthmatic mice were also associated with fewer proliferating Th2 and ILC2 as compared with their normal-weight asthmatic littermates after the experimental induction of allergic asthma." (PMID 35888038, 2022). "Thus, leptin emerges as a potential mediator driving allergic asthma." (PMID 29891850, 2018). "Interestingly, the presence of leptin has been suggested to be necessary for the induction and maintenance of the pro-inflammatory Th1 immune response, the response contrary to Th2 that is observed in allergic asthma." (PMID 23383125, 2013). "We have observed above increases in leptin expression in HFD mice compared with their ND controls, and during allergic asthma, HFD T cells expressed higher amounts of XBP1s." (PMID 29891850, 2018). "However, as a potential mediator driving allergic asthma, leptin is still in lack of being understood on how it participates in defective metabolism-involved lung pathology." (PMID 29891850, 2018).
amyotrophic lateral sclerosis (6 papers, 2017 to 2023). Amyotrophic lateral sclerosis (ALS) is a neurodegenerative disease characterized by progressive muscular paralysis reflecting degeneration of motor neurons in the primary motor cortex, corticospinal tracts, brainstem and spinal cord. "A population-based study showed decreased leptin levels in patients with amyotrophic lateral sclerosis which was mainly related to a decrease in BMI." (PMID 36432490, 2022). "Leptin has been suggested to play a role in amyotrophic lateral sclerosis (ALS), a fatal progressive neurodegenerative disease." (PMID 34638645, 2021). "Targeting leptin could represent a rational strategy to treat amyotrophic lateral sclerosis (ALS), as previously clinical studies have shown its levels to be associated with a lower risk of ALS disease." (PMID 34935299, 2022).
Ascites (6 papers, 2013 to 2020). Accumulation of fluid in the peritoneal cavity (between the layers of the peritoneum that lines the abdomen). "Whether leptin release from fat depots is changed in the patients or is even raised in intraabdominal adipose tissues of those patients with ascites needs further clarification." (PMID 28661458, 2017). "Leptin is neither changed in patients with ascites, nor in those with esophageal varices." (PMID 28661458, 2017). "The borderline statistical significance (P = 0,054) of leptin level differences in subgroups with and without ascites was found and might suggest its negative influence on the evolution of ALD." (PMID 24259947, 2013).
atopic dermatitis (6 papers, 2013 to 2024). "The leptin issue remains contentious as other researchers failed to conclusively confirm its role in shaping atopic eczema in children and there is a lack of studies in adults." (PMID 32899610, 2020). "Interestingly, studies showed the differences in leptin levels according to types of dermatitis, IgE-mediated and non-IgE mediated atopic dermatitis." (PMID 33008429, 2020).
atrial fibrillation (6 papers, 2017 to 2024). A disorder characterized by an electrocardiographic finding of a supraventricular arrhythmia characterized by the replacement of consistent P waves by rapid oscillations or fibrillatory waves that vary in size, shape and timing and are accompanied by an irregular ventricular response. "In patients with paroxysmal atrial fibrillation, leptin levels were correlated with the parameters of cardiac autonomic function." (PMID 35955485, 2022). "It has been shown in rats that leptin contributes to atrial fibrosis and angiotensin II-evoked atrial fibrillation." (PMID 35955485, 2022).
autonomic neuropathy (6 papers, 2013 to 2025). An inherited or acquired peripheral neuropathy affecting the autonomic nervous system. "Since high levels of leptin were associated with autonomic neuropathy in diabetic patients and these patients presented decreased muscle strength, we hypothesized that a relationship could exist between leptin and respiratory function." (PMID 30208912, 2018). "In contrast, a Turkish study (mean age, ~57 years; mean BMI, ~28 kg/m2) found that the plasma leptin levels in diabetic patients with Sensorial neuropathy (n=38) or autonomic neuropathy (n=13) were not statistically different from those without these complications." (PMID 39735639, 2024).